CNOT3 (CCR4-NOT transcription complex subunit 3)
Diseases named in the same sentence as CNOT3 in open-access papers (continued):
Sharing a sentence is not in itself a finding about the gene and the disease.
cerebral atherosclerosis (1 paper, 2021). Atherosclerosis of the cerebral vasculature. "The assumptions for mediation analysis were met for both SNPs: they were associated with cerebral atherosclerosis and CNOT3 protein level, and CNOT3 protein level was associated with cerebral atherosclerosis after adjusting for 8 other neuropathologies." (PMID 34073619, 2021). "Notably, CNOT3 protein has evidence for physical interactions in the BioGRID dataset with two proteins we previously found associated with cerebral atherosclerosis in human brain, HNRNPLL and RTF1." (PMID 34073619, 2021). "We used formal mediation analysis to test the hypothesis that the SNPs influence cerebral atherosclerosis risk through their effect on CNOT3." (PMID 34073619, 2021). "The results suggest that the SNPs may influence cerebral atherosclerosis risk partially through CNOT3 (rs6664221: mean indirect effect = −0.05, 95% CI = (−0.0952, −0.01), bootstrap p < 0.004; rs10881463: mean indirect effect = −0.05, 95% CI = (−0.0959, −0.02), bootstrap p < 2 × 10−16; N = 352)." (PMID 34073619, 2021). "We further found that the SNPs may influence cerebral atherosclerosis by regulating brain protein expression of CNOT3." (PMID 34073619, 2021). "We identified a novel genetic locus for cerebral atherosclerosis and found evidence that it may act by regulating brain protein levels of CNOT3." (PMID 34073619, 2021). "In conclusion, we identified a novel risk locus in NTNG1 that may contribute to cerebral atherosclerosis severity by mediating brain protein levels of CNOT3, a sub-unit of the master regulator CCR4−NOT." (PMID 34073619, 2021).
deficiencies (1 paper, 2025). "De novo mutations in human CNOT3 cause severe neurodevelopmental deficiencies characterized by a spectrum of intellectual disability, speech delay, seizures, and behavioral problems." (PMID 39913536, 2025).
diabetes (1 paper, 2020). "We show that β-cell-specific knockout (KO) of Cnot3 results in impaired glucose tolerance and ultimately the development of overt diabetes." (PMID 32859966, 2020). "The authors found that Cnot3 was dysregulated in diabetic mice and, when knocked out in wild type, mice have impaired glucose tolerance and gradually develop diabetes." (PMID 32859966, 2020). "Mice with β cell-specific Cnot3 deletion (Cnot3βKO) exhibit impaired glucose tolerance, decreased β cell mass, and they gradually develop diabetes." (PMID 32859966, 2020). "It further raises the possibility that CNOT3 might offer a promising therapeutic target to protect β-cell function or to generate β cells for treatment of diabetes." (PMID 32859966, 2020). "In conclusion, our work identifies CNOT3 as an important post-transcriptional regulator of β-cell identity and function, and raises the possibility that alterations in CNOT3 expression and/or dysregulation of the CCR4–NOT complex contribute to β-cell failure in diabetes." (PMID 32859966, 2020).
eye cancer (1 paper, 2018). "Here, we explored how loss of Not3, the CNOT3 orthologue, is involved in tumor development using loss-of-function and gain-of-function analyses in Drosophila melanogaster eye cancer models." (PMID 30144809, 2018). "Here, we use different Drosophila melanogaster eye cancer models to study the potential tumor suppressor function of Not3, the CNOT3 orthologue, and other members of the CCR4-NOT complex." (PMID 30144809, 2018).
Fanconi anemia (1 paper, 2018). Fanconi anemia (FA) is a hereditary DNA repair disorder characterized by progressive pancytopenia with bone marrow failure, variable congenital malformations and predisposition to develop hematological or solid tumors. "Among these are polymerase (DNA directed), epsilon, catalytic subunit (POLE); PTEN; Fanconi anemia, complementation group A (FANCA); and CCR4-NOT transcription complex, subunit 3 (CNOT3) and others." (PMID 30143704, 2018).
gastric cancer (1 paper, 2020). A primary or metastatic malignant neoplasm involving the stomach. "On the other hand, low-level expression of CNOT3 is associated with enhanced survival in ovarian and gastric cancers." (PMID 33138308, 2020).
Hyperglycemia (1 paper, 2020). An increased concentration of glucose in the blood. "We observed significant downregulation of Mafa, Ins1, and Ins2 mRNAs, and significant upregulation of Aldob, Slc5a10, Wnt5b, Hk1, and Tnfrsf11b mRNAs, suggesting that the molecular defect results directly from the loss of Cnot3, rather than to hyperglycemia." (PMID 32859966, 2020).
Intellectual disability (1 paper, 2025). "Mutations in CNOT3 as well as another component, CNOT1, are linked to neurodevelopmental pathologies characterized by a spectrum of intellectual disability, speech delay, seizures, and behavioral problems." (PMID 39913536, 2025).
lung adenocarcinoma (1 paper, 2023). A carcinoma that arises from the lung and is characterized by the presence of malignant glandular epithelial cells. "We noticed that the expression of CNOT3 was higher in lung adenocarcinoma with HER2 overexpression." (PMID 37919290, 2023). "We consulted the RNA-seq datasets of the TCGA database and noticed CNOT3 expression was positively correlated with the expression of some ErbB family of receptor tyrosine kinases such as EGFR, ErbB-2 (neu, HER2) and ErbB-3 (HER3) in lung adenocarcinoma." (PMID 37919290, 2023).
lung carcinoma (1 paper, 2023). "Together, our findings will give novel insights into the role of CNOT3 in lung cancer malignancy and provide a promising strategy to resolve both EGFR-TKIs resistance and tumor progression." (PMID 37919290, 2023). "Our previous study has proposed the up-regulation of CNOT3 in lung cancer." (PMID 37919290, 2023). "In this study, we showed that the expression of CNOT3 could be regulated by EGFR signaling in lung cancer." (PMID 37919290, 2023). "In the present study, we found in lung cancer cells the expression of CNOT3 could be regulated by EGFR signaling pathway and c-Jun, a transcription factor downstream of EGFR, transcriptionally regulated its expression." (PMID 37919290, 2023). "Our findings may also give an explanation on the overexpression of CNOT3 in lung cancer." (PMID 37919290, 2023). "We propose that the dysregulated c-Jun/CNOT3 axis can contribute to EGFR-TKIs resistance and CNOT3 is a potential target to enhance the chemosensitivity of lung cancer cells to EGFR-TKIs and to prevent metastatic progression." (PMID 37919290, 2023). "Thus, further up-regulation of CNOT3, which was due in part to HER2 overexpression-induced dysregulation of the c-Jun/CNOT3 axis, dampened gefitinib sensitivity in lung cancer cells." (PMID 37919290, 2023). "CNOT3, a subunit of the CCR4-NOT complex, has recently been suggested to be overexpressed in lung cancer and involved in tumor malignancy." (PMID 37919290, 2023).
microcephaly (1 paper, 2025). A congenital or acquired developmental disorder in which the circumference of the head is smaller than normal for the person's age and sex. "Collectively, our analysis of dcKO mice suggests that Cnot3-dependent microcephaly and neuronal loss are due in part to massive apoptosis." (PMID 39913536, 2025).
moyamoya angiopathy (1 paper, 2021). "More rarely, CNOT3 variants have been associated with unilateral/bilateral moyamoya angiopathy (MMA), a vascular trait conferring increased risk to strokes starting in childhood through the fourth decade of life." (PMID 34208845, 2021).
myeloid leukemia (1 paper, 2024). A clonal proliferation of myeloid cells and their precursors in the bone marrow, peripheral blood, and spleen. "Here, we uncovered CNOT3, a subunit of the CCR4-NOT complex, as an essential modulator of translation in myeloid leukemia." (PMID 38491013, 2024).
myocardial infarction (1 paper, 2017). Gross necrosis of the myocardium, as a result of interruption of the blood supply to the area, as in coronary thrombosis. "To test that, we injected lentivirus overexpressing Cnot3 into mouse hearts immediately after myocardial infarction surgery and evaluated local cardiomyocyte proliferation 21 days post-surgery." (PMID 28473716, 2017).
oral cancer (1 paper, 2019). "In conclusion, next-generation sequencing analysis revealed that a total of 13 genes (RRP43, RRP42, CSL4, TRF4, Mtr4, RRP6, MPP6, CNOT2, CNOT3, SKI2, Ski3, EDC4, and XRN1) involved in the mRNA degradation pathway were upregulated by PPARα activation in oral cancer cells." (PMID 31724941, 2019).
osteoporosis (1 paper, 2017). A condition of reduced bone mass, with decreased cortical thickness and a decrease in the number and size of the trabeculae of cancellous bone (but normal chemical composition), resulting in increased fracture incidence. "While deletion of both Cnot3 alleles is embryonically lethal, heterodeficient Cnot3 mice show cardiac dysfunction, increased osteoporosis and increased hepatic expression of mRNAs encoding catabolic enzymes." (PMID 28615693, 2017).
retinal degeneration (1 paper, 2012). Degeneration of the retina. "In asymptomatic carriers CNOT3 is expressed at low levels, allowing higher amounts of wild-type PRPF31 transcripts to be produced and preventing manifestation of retinal degeneration." (PMID 23144630, 2012).
vascular malformation (1 paper, 2023). A non-neoplastic disorder that is the result of defects of vascular morphogenesis. "This includes some of the genes for moyamoya phenomenon, other vascular malformations, abnormalities of coagulation including CBL, DIAPH1, CHD4, CNOT3, and SETD5." (PMID 36253534, 2023).
tumor (11 papers, 2017 to 2025). "From our analyses, CNOT3 alterations (mutations, deletions, and amplifications) are common across multiple types of cancers in sequenced patient and cell line tumor samples." (PMID 31231471, 2019). "Thereafter, we tested if the results obtained in Drosophila could be translated to human T-ALL, since CNOT3 mutations were described in this tumor type." (PMID 30144809, 2018). "In contrast, the expression of ELAVL2, RAD9B and CNOT3, already identified as tumor suppressor, and inhibitors of cell cycle progression, respectively, were upregulated by the miR-Combo." (PMID 37749143, 2023). "The results showed there were some Keratin 7-positive cells in the lymph node, suggesting gefitinib treatment adversely triggered the metastasis of some drug-resistant tumor cells and CNOT3 depletion prevented it." (PMID 37919290, 2023). "CNOT3 is also found to be aberrantly expressed in tumor and to play a role in promoting tumor formation and progression." (PMID 37919290, 2023). "Alterations in CNOT3 expression can be observed in many types of cancer which subsequently induces alterations in cell functions and contributes to tumor malignancy." (PMID 37919290, 2023). "It revealed that CNOT3 depletion enhanced the anti-tumor effect of gefitinib in PC-9 GR cells as long as we prolonged treatment." (PMID 37919290, 2023). "Even so, the function of CNOT3 in cancer is still not fully known and its involvement in the resistance to other anti-tumor therapeutics remains elusive." (PMID 37919290, 2023). "Knockdown of CNOT3 led to tumor formation in a sensitized Drosophila melanogaster model and inflammatory phenotypes in mice." (PMID 34680937, 2021). "We demonstrated CNOT3 depletion was able to inhibit tumor growth in vivo." (PMID 37919290, 2023). "In this study, we discussed about whether CNOT3 would be a potential target to overcome gefitinib resistance as its expression was negatively correlated with the anti-tumor efficacy of gefitinib." (PMID 37919290, 2023). "In human cancer, only one allele of CNOT3 is mutated, suggesting that this is sufficient to contribute to tumor development and that complete loss of CNOT3 is not viable for the cells." (PMID 30144809, 2018). "Since Not5 in particular appears to be involved in the regulatory loop linking translation to amino acid biosynthesis, the ortholog CNOT3 may have a tumor suppressor function." (PMID 28588606, 2017). "It is important to note that an impact of CNOT3 on amino acid biosynthesis is unlikely to be the only mechanism, by which a mutation of CNOT3 in tumor cells might contribute to tumor survival." (PMID 28588606, 2017). "However, it still remains unclear how mutations on CNOT3 or other CCR4-NOT subunits can contribute to tumor development." (PMID 30144809, 2018). "Knockdown of CNOT3, a subunit incorporated in the CCR4-NOT complex and responsible for deadenylase activity, was shown to induce tumour development in a sensitized drosophila eye cancer model." (PMID 31572192, 2019). "In solid tumors, recent reports show that CNOT3 and other CCR4-NOT subunits could be involved in tumor formation/progression." (PMID 30144809, 2018).
cancer (9 papers, 2017 to 2024). A tumor composed of atypical neoplastic, often pleomorphic cells that invade other tissues. "Our work is the first to provide evidence that the CNOT3 E70K mutation, a common but previously uncharacterized mutation in cancers, is an inactivating mutation." (PMID 31231471, 2019). "Given the important role of c-MYC in cancer and leukemogenesis, we further investigated the functional relationship between CNOT3 and c-MYC." (PMID 38491013, 2024). "Thus, Not3/CNOT3 loss could contribute to cancer development through those two signaling pathways." (PMID 30144809, 2018). "This suggests that in metazoans a common function implicating ribosome subunits and CNOT3 plays a role in the development of cancer." (PMID 28588606, 2017). "In this study, we presented a conclusive evaluation of CNOT3 functional interaction with c-MYC, a critically important oncogene in cancer." (PMID 38491013, 2024). "The two genes CNOT1 and CNOT3 were also identified to be involved in a type 2 sub-network, and be enriched in RNA degradation (pathway ID 03018), where CNOT3 is a NCG cancer gene." (PMID 28415609, 2017). "Intriguingly, target genes of all four factors (Cnot3, Trim28, c-Myc, and Zfx) are enriched for cancer genes (as determined by Ingenuity Pathway Analysis) supporting the idea that regulatory networks controlling self-renewal in stem cells may also be active in certain cancers." (PMID 28851455, 2017).
infection (2 papers, 2018 to 2023). The state of being infected such as from the introduction of a foreign agent such as serum, vaccine, antigenic substance or organism. "Depletion of CNOT1 led to an 85 and 72% reduction in infection with siRNAs #1 and #2, respectively, while CNOT3 targeting led to reductions of 92 and 80%." (PMID 37846490, 2023). "Very similar temporal effects on viral protein accumulation were observed over a time course of infection of CNOT3‐depleted cells (Fig EV2D)." (PMID 37846490, 2023). "CNOT1 and CNOT3 proteins dramatically increased during infections with both virus strains beginning at 24 HPI." (PMID 37846490, 2023). "By contrast, infection with clinical HCMV strain TB40/E was acutely sensitive to CNOT1 and CNOT3 depletion, displaying reduced accumulation of proteins representing each viral temporal gene class in knockdown cells." (PMID 37846490, 2023). "At 72 h post infection (HPI), late in the virus lifecycle, accumulation of representative proteins from each temporal gene class was impaired when CNOT1 or CNOT3 were targeted by either of two independent siRNAs." (PMID 37846490, 2023). "To decipher how CNOT1 and CNOT3 promote viral replication, we examined the abundance of viral proteins and transcripts in a synchronous high MOI (multiplicity of infection) infection." (PMID 37846490, 2023). "Following infection of HeLa cells with either Ad5 or Ad12, levels of CNOT1, CNOT3, CNOT4, and CNOT7 were monitored by Western blotting." (PMID 29593045, 2018). "However, the levels of both CNOT3 and CNOT7 were markedly reduced after infection with both serotypes." (PMID 29593045, 2018). "Interestingly, mRNA levels for CNOT1, 2, and 3 increased by a maximum of twofold compared to uninfected cells during infections, suggestive of a translational modality to CNOT1 and CNOT3 protein upregulation, a feature previously reported for the regulation of CNOT3 expression in response to diet." (PMID 37846490, 2023). "CNOT1 or CNOT3 depletion did not measurably impact the accumulation of VACV proteins, detected using a pan‐VACV antibody, or the accumulation of IE, early and late HSV‐1 proteins ICP4, US3, or gC following a low multiplicity infection." (PMID 37846490, 2023).
cardiac diseases (1 paper, 2017). "Thus, it will be interesting to explore whether ectopically expressed Cnot3 in adult hearts underlies cardiac diseases." (PMID 28473716, 2017). "Collectively, these results indicate that Cnot3 manipulation is an effective means to enhance cardiomyocyte proliferation and improve heart function in heart diseases." (PMID 28473716, 2017).
CNOT3 also shares sentences with these, for which no sentence is quoted: speech delay (3 papers); retinitis pigmentosa (2); adenocarcinoma (1); adult T-cell acute lymphoblastic leukemia (1); brain tumor (1); colon adenoma (1); craniosynostosis (1); dysmorphic facies (1); eye tumors (1); genetic disorders (1); lymphoma (1); male infertility (1); steatosis (1).